CXCL10 (C-X-C motif chemokine ligand 10)
Diseases named in the same sentence as CXCL10 in open-access papers (continued):
Sharing a sentence is not in itself a finding about the gene and the disease.
infection (continued). "DC isolated early after infection of pigs with either of the two CSFV strains showed prominent upregulation of CCL5, CXCL9, CXCL10, CXCL11, and XCL1, as well as of the cytokines TNFSF13B, IL6, IL7, IL12B, IL15, IL27." (PMID 32733474, 2020). "For example, high levels of CXCL-10/IP-10, CCL-2/MCP-1, CXCL-5/RANTES, and CCL-3/MIP-1α enhance the recruitment of dendritic cells and macrophages to the site of infection." (PMID 32922406, 2020). "In particular, in model systems using virus-infection to induce the autoimmune destruction of β-cells, such as the RIP-LCMV mouse model, CXCL10 was among the first chemokines upregulated in the pancreas upon LCMV-infection." (PMID 33193102, 2020). "Importantly, it should be noted that the anti-CXCL10 antibody treatment started before initiation of the disease by LCMV-infection and therefore like using CXCL10-deficient mice the CXCL10 neutralization constituted a preventive rather than a therapeutic intervention." (PMID 33193102, 2020). "infection, whereas the corresponding early responding genes in SCC cells were IL10, IL1β, IL1α, TNF, CXCL10, CXCL1, HBEGF, IL6, and CSF3." (PMID 31912662, 2020). "As they have a common receptor (CXCR3), CXCL9, CXCL10, and CXCL11 have generally been studied together, and studies of combinations of CXCL9, CXCL10, and CXCL11 in infection, injury, and immunoinflammatory responses have been conducted." (PMID 31836011, 2019). "With a high MOI infection of 75 TCID50/ml both viruses induced IFN-λ1, IFN-β and CXCL10 mRNA expression relatively well in DCs with GWUH strain showing ca. 10-fold higher cytokine mRNA levels than the African #976 strain." (PMID 31673117, 2019). "The infection of human macrophages induced the expression of pro-inflammatory cytokines/chemokines such as MCP-1/CCL-2, IFN-α2, IFN-γ, MIP-1α/CCL-3, IP-10/CXCL-10, RANTES/CCL-5, IL-8, TNF-α, IL-12p40, and IL-6." (PMID 30984127, 2019). "In neuronal cultures, infection with HSV-1 upregulated IFN-alpha, TNF-alpha, CXCL9, and CXCL10, while addition of NO downregulated all tested cytokines and chemokines." (PMID 30886672, 2019). "CXCR3 and its ligands, the IFN-γ-inducible C-X-C chemokines CXCL9, CXCL10, and CXCL11, are important for migration of activated CD4+ Th1 cells to inflamed tissues and sites of infection." (PMID 30915078, 2019). "Nonetheless, PKR is important for the production of IFN-I, IL6, CCL2, and CXCL10 in primary SJL astrocyte cultures, whereas TLR3 plays only a minor role in the responses to a TMEV-BeAn infection." (PMID 30669615, 2019). "We observed a strong transcriptional induction of the pro-inflammatory cytokine CXCL10 and lower levels of IFNβ in BKV-infected undifferentiated podocytes sustained over 96 h post-infection." (PMID 31252545, 2019). "Compared to mock infection, RSV infection via both inoculation methods resulted in increased BAL concentrations of CCL2 (MCP-1), CCL5 (RANTES), CXCL1, CXCL10 (IP10), IFN-α, IFN-γ, and TNF." (PMID 31163619, 2019). "The authors also observed significant induction of CXCL10 and IFNβ expression in BKV-infected cells that correlated with increased virus replication over a time course of infection." (PMID 31533282, 2019). "Consistently, mRNA levels of IFNB1, ISG56, CXCL10, and IL6 genes induced by HCMV-ΔUL42 were significantly higher than those induced by HCMV-WT at 6, 12, and 24 hr post-infection in HFFs, human primary monocyte-derived dendritic cells and macrophages." (PMID 31107917, 2019). "Our results showed that Hypr infection of HBCA induced increased production of numerous cytokines/chemokines—particularly CCL5 (RANTES), CXCL10, IL-6, and IL-8, which confirmed our previous findings." (PMID 31699097, 2019). "The authors also observed induction of CXCL10 and IFNβ transcriptional in BKV-infected podocytes that correlates with increased viral replication over the course of infection." (PMID 31533282, 2019).
infection (continued). "T-cells can be directed to the infection site by type-I IFN stimulated secretion of IL-10 and CXCL10." (PMID 30984127, 2019). "Elevated expression of the chemokine CXCL10 was detected in VA1-infected primary astrocytes and SK-N-SH cells, suggesting that VA1 infection can induce a proinflammatory host response." (PMID 31289185, 2019). "In macrophages, instead, the infection with the African ZIKV #976 strain led to somewhat higher IFN-λ1, IFN-β and CXCL10 mRNA expression levels as compared to those induced by the GWUH strain." (PMID 31673117, 2019). "At T1, 2 months post-infection, the LM17- and LJL143-immunized dogs presented higher levels of IFN-γ, IL-6, IL-18, CXCL10, GM-CSF, IL-7, IL-15, and CCL2 in comparison to controls." (PMID 30519235, 2018). "Increased levels of D-dimer, IL-6, sCD14, CXCL10, TNF-α, IL-18, and CCL2 among others have been shown to be increased during acute infection or chronically increased throughout infection." (PMID 29391069, 2018). "IL6, IFNB1, CXCL10, and CCL5 gene expression was significantly elevated in ATII cells following infection and was reduced by the addition of apocynin (except for IFNB1)." (PMID 30341336, 2018). "The cutoff serum concentration values for prediction of infection etiology with both sensitivity and specificity of 1 was 17.5 pg/ml for CXCL9 and 4.5 pg/ml for CXCL10." (PMID 29988532, 2018). "Although mRNA levels of all these cytokines reduced in RV-infected mice with COPD phenotype, the levels of CXCL-1, CXCL-10, CCL3, TNF-α, IL-17A and IFN-γ remained high up to 14 days post-infection." (PMID 29975735, 2018). "Chemokine expression analysis revealed that T3SS mutant induced lower mRNA levels of CXCL1, CXCL2, CXCL5, CXCL10 and CCL20 than the wild-type strain at 16 h post-infection." (PMID 30070169, 2018). "Individual stimulation of TLR3, which senses dsRNA that is expressed upon infection by most RNA viruses including influenza and RSV 6, 19, 20, 21, indeed induced IFN‐β and CXCL10 protein production." (PMID 30184252, 2018). "In particular, the levels of I-TAC (CXCL11), IP-10 (CXCL10), MIG (CXCL9), and MCP-3 (CCL7) increased nearly 6-fold upon infection." (PMID 30467502, 2018). "The infection classifier based on the combination of CXCL9 and CXCL10 serum levels was identified as the best model comprising the minimum set of biomarkers and allowing an accurate infection classification." (PMID 29988532, 2018). "Similar to CXCL10, the proliferation rate of sensory Fbs (10K) was significantly suppressed by CXCL3-siRNA infection, while the proliferation rate of motor Fbs (10K) was enhanced by CXCL 3-siRNA infection." (PMID 30686982, 2018). "As only few of the abundant number of CD4+ T cells at the site of infection express CXCR3, it seems plausible that the CXCL10/CXCR3 chemotactic axis is under regulation by DPP4 in active TB." (PMID 30026741, 2018). "Plasma levels of TNF-α, IFN-γ, IL-6, IL-10, CXCL10, CCL2 and IL-4 were all increased upon infection." (PMID 30375380, 2018). "Upon infection, epithelial cells, macrophages, and recruited neutrophils secrete CXCL10 (IP-10), which increases the chemotaxis of T cells." (PMID 30345002, 2018). "Further, in this model and others, increased levels of IP-10 (CXCL10), MCP-1 (CCL2), and IL-6 have been observed, which have been characterized as hallmarks of H5N1 human infection." (PMID 30568659, 2018). "The CXCL10 and CXCL11 were significantly induced during L2-MHV3 infection in both WT and IL-33 KO mice with an exacerbated manner especially at 72 h PI in IL-33 KO context." (PMID 28607531, 2017). "There was a strong induction of chemotactic factors, including CXCL10 and CXCL11, which are important for recruitment of monocytes/macrophages to the site of infection." (PMID 29051759, 2017). "An efficient antiviral response induces the recruitment of RSV-specific CD4+ and CD8+ T cells to the infection site by the CXCL9 and CXCL10 chemokines, which are induced by IFNs and the chemokine receptor CXCR3." (PMID 28751894, 2017).
infection (continued). "To understand the role of CD169+ cells in the recruitment of effector T cells to the infection site, we measured the CXCL9 and CXCL10 levels in BAL fluid from DT-treated WT and CD169-DTR mice after RSV infection." (PMID 28751894, 2017). "In the liver, at the beginning of infection, parasitised Kupffer cells secrete chemokines such as CCL3, CCL2 and CXCL10, which stimulate the recruitment of monocytes and granulocytes." (PMID 28767981, 2017). "Multifunctional Th17 cells (IFN-γ+IL-17A+) co-expressing CXCR3/CCR6 are known to upregulate the ligands for CXCR3 (CXCL9/CXCL10/CXCL11) on the lung parenchymal cells, which helps to recruit Th1 cells to the site of infection." (PMID 28985739, 2017). "Nonetheless, the absence of IFNγ induction in IL-33 KO and the expressions of CXCL10 and CXCL11 were strongly upregulated during L2-MHV3 infection especially in IL-33 KO background at 72 h PI." (PMID 28607531, 2017). "The production of CXCL10, CCL4 and CCL5 was markedly increased by HAV (HM-175/18f) infection in the culture of primary human hepatocytes and HepG2 cells." (PMID 28744018, 2017). "We found mRNAs of the type 1 chemokine ligands and their receptors (CCL4, CCL5, CCR5, CXCL9, CXCL10, CXCL11 and CXCR3) were increased at 21–28 days post-infection compared to uninfected controls." (PMID 28103263, 2017). "Infection of epithelial cells by IFV increases the expression of TNF-α, IL-6, IL-8, CCL2 (MIP-1), CCL5 (RANTES), CCL3 (MIP-1α), and CXCL10 (IP-10)." (PMID 28066442, 2016). "Three notable exceptions were CCL7, CXCL10 and CXCL11, which peaked (respectively) at 42.8, 35.5 and 6.6 times the level of expression at 7 days post-infection compared to the pre-infection levels." (PMID 27595844, 2016). "Investigating the predictive potential of RNA levels at 2 weeks post infection (wpi) revealed that FAM26F, MX1 and CXCL10 were predictive of chronic phase set-point viral load only when peak viraemia correlated with the further course of infection." (PMID 27902344, 2016). "Infection with both OSU and UK RVs increased the expression of IFN-β in PIE cells as well as the expression of the inflammatory cytokines and chemokines CXCL10, IL-6, IL-8 and, MCP-1." (PMID 27023883, 2016). "On the other hand, the expression of CXCL10 was induced earlier following HEP-Flury or NDV infection, suggesting its positive role in protection against initial infection of RABV." (PMID 27242764, 2016). "Among them, CXCL9, CXCL10, and CXCL11 were elevated more significantly following HEP-Flury infection at 4 dpi than CVS-11 infection." (PMID 27242764, 2016). "Upon TBwt infection, several type II ISGs (CXCL9, CXCL10, CXCL11 and IDO) exhibited varying degrees of activation at 24 h post infection in accordance with previous reports." (PMID 27387064, 2016). "CXCR3 and its ligands (CXCL9, CXCL10, CXCL11) are thought to govern the recruitment of leukocytes to the sites of inflammation and infection." (PMID 27068264, 2016). "During infection, injury, or immuno-inflammatory response, IFN-γ strongly induces the expression of CXCR3 and CXCL10 primarily on activated T cells and NK cells." (PMID 26475448, 2016). "Expression levels of CXCL10, an IFN-inducible cytokine, followed a similar upward trend as the acute infection progressed from 24 to 96 hpi, but the expression levels were down 5- and 60-fold at PST-0 and PST-15, respectively." (PMID 27222466, 2016). "CXCL10 (IP-10) and CXCL11 were two of the cytokines that were expressed in animals that succumb to infection." (PMID 27595844, 2016). "The prominent and sustained expression of CXCR3 on infiltrating CD19 B cells over the course of infection is consistent with the high-level detection of its ligands CXCL9 and CXCL10 in brain homogenates using ELISA." (PMID 27207308, 2016).
infection (continued). "Interestingly, infection with either of the three RNA viruses induced elevated levels of STING dimers in the lysates, and consistent with this, the residual induction of interferon-β and CXCL10 expression by IAV in MAVS-deficient cells was ablated when STING but not cGAS was knocked down by shRNA." (PMID 26893169, 2016). "MO-DCs emerge at day 5 and peaked at day 7 post infection with PbA, which coincides with the expression of CXCL9 and CXCL10, and other inflammatory mediators in the CNS." (PMID 27808089, 2016). "Both compounds inhibited infection, but only inhibition of reverse transcription prevented BMMC activation and CXCL10 and IFNα production." (PMID 27477283, 2016). "Preceding the influx CD3+CD8+ T-cells in this model was an increase in Th1-type chemoattractants CXCL9, CXCL10, CCL3 and CCL5 at peak primary infection." (PMID 27467505, 2016). "We found a significant increase in levels of IFN-α and IFN-β, interferon-stimulated genes (ISGs) CXCL-10 and ISG15, and the proinflammatory cytokines interleukin-6 (IL-6) and tumor necrosis factor (TNF) at 16 to 24 hpi following infection with N1040A." (PMID 27965448, 2016). "Infection activates a broad chemokine response to infection, including CXC (CXCL1, CXCL5, CXCL8, CXCL9, and CXCL10) and CC chemokines (CCL2, CCL3, and CCL5)." (PMID 26927188, 2016). "Three days post infection, sham + IAV + vehicle mice had increased mRNA expression of pro-inflammatory chemokines (CCL-2, CXCL-2, CXCL-10), cytokines (GM-CSF, TNF-α, IL-1β, IL-6) and proteases (MMP-12) compared to sham + diluent + vehicle mice." (PMID 26877172, 2016). "Infection of primary monocytes with PDK53 at both 1 and 10 MOI resulted in greater levels of CXCL10, ISG20 and IFIT2 mRNA levels compared to 10 MOI of 16681." (PMID 27185466, 2016). "Seven days post infection, CS + IAV mice had increased mRNA expression of pro-inflammatory chemokines (CCL-2, CXCL-2, CXCL-9, CXCL-10), cytokines (GM-CSF, TNF-α, IL-1β, IL-6) and proteases (MMP-12) compared to sham + IAV + diluent mice or CS + diluent mice." (PMID 26877172, 2016). "In contrast, the expression level of CXCL10, TNF-α, and IFN-γ were significantly lower in the mice vaccinated with either AlPO4- or AddaVAX-EV71 vaccines upon infection with EV71 5746 (C2) or 3340 (C4)." (PMID 26287531, 2015). "The pro-inflammatory gene expression of CXCL10, TNF-α, and IFN-γ in the CNS and muscle tissues were up-regulated in the PBS group upon infection with EV71 5746 (C2) or 3340 (C4)." (PMID 26287531, 2015). "Our data clearly show an increased expression of a set of chemokines (CCL20, CCL5, CXCL1, CXCL10, CXCL11, CCL25) normally involved in H. pylori gastritis at both 6 and 18 weeks of infection in mice, which decreased after curcumin treatment." (PMID 25569625, 2015). "M1-related chemokines CXCL9, CXCL10, and CXCL11 significantly increased after 3 weeks of infection and then declined." (PMID 24666892, 2014). "Microarray analysis revealed that the expression of CCR5, CXCR3 and CCR1 and several of their chemokines including CXCL9, CXCL10, CCL2, CCL3 and CCL9 significantly increases in response to infection in CM-affected mice." (PMID 24476686, 2014). "We have found here that infection with O. tsutsugamushi evoked an early up-regulation of innate IFN-γ, which would promote parenchymal cells to express CXCL9 and CXCL10 chemokines." (PMID 25254971, 2014). "Similar to this study, we observed significant up-regulation chemokines and cytokines, such as CCL3, CXCL10, IL1RN, IL6 and TNF, throughout infection." (PMID 25079789, 2014). "The T cell chemoattractants CXCL9, CXCL10 and CCL19 are significantly elevated in serum during the acute infection but largely return to normal levels following treatment, resolution of the erythema migrans and recovery." (PMID 24740099, 2014).
infection (continued). "In this context, there is a marked induction of CCL2, CCL3, CCL4, CCL5, CXCL8, and CXCL10 after infection with SIV, as well as a systemic increase of CCL2, CXCL8, and CXCL10 in humans, concurrently with viremia peak after infection with HIV." (PMID 25313360, 2014). "CXCL10 activates the chemokine receptor CXCR3 and is an important regulator of lymphocyte trafficking in a variety of diseases characterized by infection or inflammation." (PMID 24890566, 2014). "At day 9 post challenge, gene expression of IFN-γ and chemokines (e.g. CXCL10, CXCL11) in mock vaccinated guinea pigs, compared to C. caviae EB vaccination or naïve guinea pigs, correlated with active/ongoing infection." (PMID 25502875, 2014). "Levels of mRNAs for CCL2, CCL3L1, CCL4, CXCL10, CCR1 and CCR5 were significantly increased in at least one time point following infection in two experiments and CCL5, CCR9 and CXCR4 mRNA were significantly increased in one of the experiments." (PMID 24083897, 2013). "Those mRNAs for CCL2, CCL31, CCL4, CXCL10, CCR1 and CCR5 were significantly increased following infection in both experiments in at least one time-point and CCL5, CCR9 and CXCR4 mRNA were significantly altered in one of the experiments." (PMID 24083897, 2013). "Following infection in vitro, C. parvum sporozoites induce the production of CXCL9 and CXCL10 in IEC by a yet-unidentified mechanism." (PMID 24367259, 2013). "IEC isolated from neonates at the peak of the infection presented a clear up-regulation of XCL1, CCL3, CCL4, CCL5, CXCL9, and CXCL10 expression, with levels close to those in adults for CXCL9 and CXCL10." (PMID 24367259, 2013). "CXCR3-mediated accumulation of ASC is consistent with the sustained expression of the CXCR3 ligands CXCL9, CXCL10, and CXCL11 throughout CNS MHV-JHM infection." (PMID 23435240, 2013). "To further validate CXCL10 as a candidate for the recruitment of CD103+ DC, we analyzed their recruitment in the intestine of CXCR3−/− neonates at the early stage of the infection (3 dpi)." (PMID 24367259, 2013). "Upregulation of CXCL10 and CCL3 in the CNS and peripheral tissues after virulent 5746 infection in transgenic mice was reported by our previous works." (PMID 23936115, 2013). "The results showed that greatest fold increases in mRNAs for CXCL10 and CCL2 were observed following infection of pigs." (PMID 24083897, 2013). "The chemokines IP-10 (CXCL10), MCP-1 (CCL2) and RANTES as well as the cytokines IL-6, IL-1β IL-1Rα and IL-12 are similarly expressed early following infection and their levels correlate with viral loads." (PMID 23936572, 2013). "Among the genes belonging to the IFN pathway, CXCL10, IFNB1, IL28A and IL29 were increased after 24 h of infection." (PMID 23723976, 2013). "To further check how Fas and FasL influence the cytokine and chemokine production in vivo we assessed vaginal lavages for the production of chemokines (CXCL1, CXCL9 and CXCL10) and interleukins (IL-1β and TNF-α) at 3 and 7 day of infection." (PMID 23922974, 2013). "VACV infection induced the production of Cxcl10 and Il-6 into the bronchoalveolar lavage (BAL) fluid, however, infection with VACV vΔC16 lead to an enhanced production of these cytokines." (PMID 24098118, 2013). "One study showed that infection of mice with L. major upregulated the gene expression of several chemokines (RANTES/CCL5, MIP-1α/CCL3, IP-10/CXCL10, and MCP-1/CCL2) in cells collected from the footpad and their draining lymph nodes." (PMID 22131998, 2012). "Neutralizing CXCL10 or depletion of Asialo GM1+ cells reduced cleaved caspase 3 and TUNEL+ cells in the liver at day 1 after infection." (PMID 23050007, 2012). "In vitro infection of immature dendritic cells (imDC) with DENV-2 led to induction of CCL11/Eotaxin, CCL2/MCP-1, CCL5/RANTES, CCL3/MIP-1α and CXCL10/IP-10." (PMID 22815692, 2012).